SNRPN (small nuclear ribonucleoprotein polypeptide N)
Description:
May be involved in tissue-specific alternative RNA processing events.
Synonyms: snRNP-N; Sm-D; Sm-N; SmN; HCERN3; SNURF-SNRPN; RT-LI; PWCR
Tractability: PROTAC: ubiquitination databases record sites on it.
Gene: Protein-coding gene on chromosome 15 (24,823,637 to 24,978,723, forward strand). Ensembl gene ENSG00000128739.
Subcellular location: Nucleus
Subcellular location (Human Protein Atlas): Nucleoplasm
Pathways (Reactome):
Metabolism of RNA: mRNA Polyadenylation; mRNA Splicing - Major Pathway
Chromatin organization: CHD1 and CHD2 subfamily
Disease: Dengue Virus-Host Interactions
Gene Ontology:
Molecular function: protein binding; snRNP binding; RNA binding
Biological process: mRNA splicing, via spliceosome; RNA splicing
Cellular component: catalytic step 2 spliceosome; cytoplasm; nucleoplasm; small nuclear ribonucleoprotein complex; spliceosomal complex; U1 snRNP; U2 snRNP; U2-type prespliceosome; U4 snRNP; U4/U6 x U5 tri-snRNP complex; U5 snRNP; nucleus
Genetic constraint (gnomAD): Loss-of-function variants: 6 observed, 23.53 expected, observed/expected ratio (o/e) 0.26, 90% interval 0.14 to 0.5. The upper end of that interval is the gene's LOEUF score, 0.5, which puts it in group 2 of 6, group 1 being the genes least tolerant of losing a copy. Missense variants: 189 observed, 327.01 expected, observed/expected ratio (o/e) 0.58, 90% interval 0.51 to 0.65. Synonymous variants: 119 observed, 110.78 expected, observed/expected ratio (o/e) 1.07, 90% interval 0.93 to 1.25.
Homologues: Orthologues: macaque SNRPN (100% identical), mouse Snrpn (100% identical), chimpanzee SNRPN (99% identical), guinea pig SNRPN (99% identical), rat Snrpn (96% identical), dog SNRPN (95% identical), pig SNRPN (91% identical), Caenorhabditis elegans snr-2 (37% identical). Paralogues in human: SNRPB (88% identical).
Diseases named in the same sentence as SNRPN in open-access papers:
SNRPN is named in the same sentence as 84 diseases in open-access papers, as found by Europe PMC text mining. Sharing a sentence is not in itself a finding about the gene and the disease. The quoted sentences say what the papers report.
Prader-Willi syndrome (39 papers, 2005 to 2025). "Other potential genetic causes of this phenotype, Prader-Willi syndrome and Fragile X syndrome, had previously been excluded in the proband by SNRPN DNA methylation analysis and demonstration of normal 5’-UTR CGG repeat number in the FMR1 gene." (PMID 26120850, 2015). "The Angelman/Prader-Willi syndrome (AS/PWS) domain contains at least 8 imprinted genes regulated by a bipartite imprinting center (IC) associated with the SNRPN gene." (PMID 23390487, 2013). "SNRPN is located within an imprinted gene cluster in chromosome 15 that is associated with Prader-Willi syndrome (PWS; OMIM 176270) and Angelman syndrome (OMIM 105830)." (PMID 21750708, 2011). "The maternally imprinted SNRPN gene has been extensively studied in mice and humans due to its association to Angelman and Prader-Willi syndromes; it has now also been putatively linked to ART and infertility." (PMID 19200381, 2009). "The larger, more proximal PWS domain encompasses five paternally expressed (maternally silenced) genes responsible for Prader-Willi syndrome, including SNRPN, which encodes the SmN antigen." (PMID 17069464, 2006). "SNRPN is linked to Prader-Willi syndrome and is involved in pre-RNA processing and splicing." (PMID 34006907, 2021). "In humans, SNRPN deletions cause Prader-Willi syndrome, characterized by polyphagia and temper tantrums, which are time-limited crises of aggressive and violent behavior that subside, succeeded by the calm and agreeable temperament described for these patients as typical." (PMID 28125592, 2017). "Interestingly, rs3913226 (between NPAP1 and SNRPN) is located within chromosome 15q11–13, a region associated with Prader-Willi syndrome." (PMID 28642868, 2017). "Another novel small duplication (proband 4) was located adjacent to SNRPN, a gene implicated in Prader-Willi syndrome (PWS)." (PMID 18925931, 2008). "Genes encoded within the imprinted Prader-Willi Syndrome (PWS)/Angelman Syndrome (AS) genomic loci, such as SNRPN and the lncRNA SPA2, are expressed only from the paternal allele of Chr." (PMID 38240312, 2024). "The SNRPN gene is part of the critical Prader-Willi syndrome (PWS) region, of which deletion leads to PWS, a neurodevelopmental disorder characterized by hypotonia, feeding difficulties, motor delay, and cognitive impairments." (PMID 36134658, 2022). "This diagnostic study examines the feasibility of screening newborns for the chromosome 15 imprinting disorders Angelman syndrome, Prader-Willi syndrome, and chromosome 15 duplication syndrome using SNRPN methylation analysis." (PMID 34982160, 2022). "Further investigation of OMIM database revealed that NDN and SNRPN are listed as candidate genes for Prader-Willi syndrome and that cryptorchidism is present frequently in the clinical picture of this syndrome." (PMID 30093884, 2018). "Comparative genomic hybridization (CGH) and SNRPN 15q methylation (for Prader-Willi syndrome) were normal." (PMID 28859103, 2017). "SNRPN was the first expressed gene identified in the Prader-Willi syndrome (PWS) critically deleted region." (PMID 25571951, 2015). "Similar ChIP in human cells shows that the CpG island of NDN and the Prader-Willi syndrome imprinting center (located in exon 1 of the SNRPN gene) carry H3K4me2 and H3K4me3 marks on the expressed paternal allele but not on the nonexpressed maternal allele." (PMID 23819640, 2013). "SNRPN has been proposed as a likely candidate gene for Prader-Willi syndrome." (PMID 36710277, 2023). "Moreover, SNRPN, one of the deleted genes for Prader-Willi syndrome, is also directly connected to the DLG4 gene." (PMID 24410907, 2014). "For example, a deletion of the paternal copies of the imprinted SNRPN gene and necdin gene on chromosome 15 located in the region 15q11–13 may result in a genetic disorder called Prader-Willis syndrome." (PMID 18346281, 2008).
Prader-Willi syndrome (continued). "Finally, Nr4a1 may serve as a potential drug target for SNRPN-related neurodevelopmental disabilities, including Prader-Willi syndrome (PWS) and autism spectrum disorders (ASDs)." (PMID 27430727, 2016). "Similarly, in the tammar wallaby, UBE3A and SNRPN (the only two genes of the orthologous Prader Willi Syndrome - Angelman Syndrome domain that could be identified) are located on different chromosomes and are not imprinted." (PMID 22899817, 2012). "In Prader-Willi syndrome (PWS), patient 3 exhibited hypermethylation of SNRPN gene, array CGH detect a large segment of UPD15." (PMID 40730975, 2025). "However, H3K9me3 levels throughout the Prader-Willi syndrome (PWS) locus encompassing SNRPN, were similar between WT and ATF7IP-KO or SETDB1-KO." (PMID 34795250, 2021). "It has been established that the paternal absence of SNRPN contributes to Prader-Willi syndrome." (PMID 37932671, 2023). "In a trio study design, two SNPs in SNRPN showed marginal imprinting effects and a balanced chromosomal abnormality was identified in an individual with ASD without Angelman syndrome or Prader-Willi syndrome." (PMID 36710277, 2023). "It should also be noted that individuals with Prader-Willi Syndrome (PWS) as a result of maternal uniparental disomy (i.e. two maternal copies of 15 and thus no paternal specific expression at the SNRPN locus) have also been reported as having more autism like features than PWS deletion individuals." (PMID 21235769, 2011).
Angelman syndrome (24 papers, 2006 to 2025). A neurogenetic disorder characterized by severe intellectual deficit and distinct facial dysmorphic features. "Dysregulation of SNRPN has been linked to Prader−Willi and Angelman syndromes, which share phenotypic overlaps with ASD, including intellectual disability and behavioral abnormalities." (PMID 40330750, 2025). "For example, ART-associated Angelman syndrome associated with hypomethylation at the SNRPN imprinting control region had been previously reported." (PMID 35071778, 2022). "The interacting partner, the small nuclear ribonucleoprotein polypeptide N (SNRPN) gene located on the 15q11-q13 region of the human chromosome, encodes for the SmN protein and is also associated with Prader–Willi syndrome/Angelman syndrome (PWS/AS)." (PMID 37511433, 2023). "Recently, the female was diagnosed with Angelman Syndrome using the PRC test based on the allelic methylation differences at the SNRPN locus (15q11.2)." (PMID 32722525, 2020). "Some Angelman syndrome cases, as well as autism and ASD, are associated with coding mutations and methylation defects at the imprinted SNRPN locus." (PMID 24667089, 2014). "The imprinted genes include those associated with BWS, such as IGF2, KCNQ1, CDKN1C, KCNQ1OT1; others such as ASCL2, HAND1, DIO3; and SNRPN, a gene in the Prader-Willi and Angelman syndrome locus." (PMID 20205951, 2010). "Moreover, a cluster of genes in the BTA21 (GABRG3, MAGEL2, MKRN3, NDN, SNRPN, and SNURF) was significantly associated (FDR = 1.07 × 10−6) with the Prader-Willi and Angelman syndromes pathway in the PPI analysis." (PMID 35692843, 2022). "The patient was originally referred to our laboratory because of suspected Angelman syndrome, which was ruled out as SNRPN methylation analysis showed a biparental pattern and no UBE3A gene mutation was found." (PMID 22475481, 2012). "The PWS diagnosis was largely excluded by the normal SNRPN gene methylation studies which ruled out genetic defects of the PWS/AS (Angelman syndrome) region." (PMID 22043167, 2011). "The SNRPN site is equivalent to the imprinting centre (IC) of the human gene which has been shown to be aberrantly methylated in the Prader-Willi (PWS) and Angelman syndromes." (PMID 20205951, 2010). "Angelman syndrome, suspected for facial dysmorphisms and absent language, was also excluded because of the presence of a normal pattern of methylation at SNRPN locus." (PMID 20205897, 2010).
autism (15 papers, 2011 to 2024). Persistent deficits in social interaction and communication and interaction as well as a markedly restricted repertoire of activity and interest as well as repetitive patterns of behavior. "In parallel, evidence suggests that chromosome segment 15q11–q13 is involved in autism spectrum disorders, and SNRPN as one of the autism-related genes." (PMID 38398047, 2024). "SNRPN had been found as a autism-related gene by regulating cortical and spine development via nuclear receptor." (PMID 32047515, 2019). "Nine SNPs (rs8025849 in NIPA1, rs3812922 in NIPA2, rs1009153 and rs2289818 in CYFIP1, rs8037745 in SNRPN, rs12438141 and rs1863467 in GABRB3, rs7403021 and rs7180500 in GABRG3) were nominally associated with autism under the recessive model (p < 0.05)." (PMID 30108208, 2018). "For other genes, such as SNRPN, CYFIP1, and ATP10A, a few SNPs or haplotypes were found to be nominally associated with autism in Europeans20,24–26." (PMID 30108208, 2018). "Moreover, even PWS and AS specific genes that lie in the BP2-BP3 PWS/AS region, such as, MAGEL2, SNRPN, UBE3A, and ATP10A are also significantly co-associated with autism (Malacards.org; SFARI.org)." (PMID 32384786, 2020). "Moreover, 7 SNPs (rs3812922 in NIPA2, rs8037745 in SNRPN, rs4906771 and rs1345098 in ATP10A, rs12438141, rs1863467, and rs4906902 in GABRB3) displayed nominal association with autism under the additive model in our samples (p < 0.05)." (PMID 30108208, 2018). "Gain in copy number of maternally-derived SNRPN has been associated with autism, but Patient 2 had not presented with such features." (PMID 24959201, 2014). "In our investigation of dup15q human cortex samples, however, SNRPN levels were significantly lower than in controls, a result that we did not expect, since all of the samples (control, autism and dup15) should express one copy of the SNRPN gene from the single paternal allele present." (PMID 22152151, 2011). "Cases I and II, are carriers of the same duplication on chromosome 15 [15q11.2q13.1(SNRPN,UBE3A,ATP10A,GABRB3,OCA2) x3], both have severe autism but with different levels of cognition." (PMID 28174603, 2017). "In contrast to both UBE3A and GABRB3, SNRPN levels were significantly negatively correlated with percentage PWS-IC methylation in all cases but not with dup15q, control or autism cases analyzed separately." (PMID 22152151, 2011).
Obesity (11 papers, 2015 to 2025). Accumulation of substantial excess body fat. "Presently, a map of genes causing obesity in pleiotropic syndromes (SNRPN gene for the obesity in PWS, GNAS1 gene in PHP1A, ALMS1 gene in ALMS, FMR1 gene in FXS, and others), has been established." (PMID 25866584, 2015). "SNRPN is a maternally imprinted gene, which is related to various neurodevelopmental disorders, and the lack of SNRPN expression has been linked to hyperphagia, loss of satiety, and obesity." (PMID 36992770, 2022). "We earlier reported that obesity was associated with lower methylation at the MEG3, SNRPN, and SGCE/PEG10 DMRs, and increased DNA methylation at MEG3-IG and H19 DMRs." (PMID 33494820, 2021). "Obesity gene panel analysis of 57 obesity-associated genes revealed a homozygous variant NM_003097.3(SNRPN):c.193C>T, p.(Arg65Trp) in exon 6 of the SNURF-SNRPN gene, changing CGG into TGG." (PMID 34200226, 2021). "SNRPN is also known to be related to the onset of obesity, and the lack of SNRPN expression results in hyperphagia, loss of satiety, and obesity in PWS." (PMID 33224876, 2020).
Infertility (7 papers, 2009 to 2024). "As far as we know, no data in the literature suggest the mechanism through which SNRPN hypermethylation impairs spermatogenesis or causes infertility." (PMID 38398047, 2024). "Through a meta-regression analysis, a direct association was found between age and higher sperm SNRPN methylation in infertile patients." (PMID 38398047, 2024). "Intriguingly, gain of methylation at mICRs (e.g., KCNQ1OT1, MEST, PLAGL1 and SNRPN) and loss of methylation at pICRs (e.g., H19) are frequently observed in spermatozoa from infertile human patients." (PMID 27880848, 2016). "Another meta-analysis reached similar conclusions, showing that the Small Nuclear Ribonucleoprotein Polypeptide N (SNRPN) gene also exhibits significantly higher methylation in patients with infertility than in fertile ones." (PMID 39338105, 2024). "The present systematic review and meta-analysis showed significantly higher methylation levels of the SNRPN gene in spermatozoa of patients with infertility/abnormal sperm parameters compared to fertile controls/normozoospermic men." (PMID 38398047, 2024). "Patients with abnormal sperm parameters/infertility showed significantly higher SNRPN methylation levels than fertile controls/men with normal sperm parameters (SMD 1.20, 95% CI: 0.47, 1.93, p < 0.001)." (PMID 38398047, 2024). "In the group of infertile patients/patients with abnormal sperm parameters, age was directly correlated to the degree of SNRPN methylation, highlighting the presence of a mechanism that explains the age-related altered sperm quality and the risk of ART." (PMID 38398047, 2024). "Our results support the presence of higher methylation levels of the SNRPN gene in the spermatozoa of patients with infertility/abnormal sperm parameters and may suggest this epigenetic deterioration as a possible cause of otherwise unexplained male infertility." (PMID 38398047, 2024). "The DNA methylation of one paternally (H19) and two maternally (SNRPN and KCNQ1OT1) methylated imprinted genes in sperm samples from 97 infertile males and 31 control subjects was analyzed by bisulfite pyrosequencing." (PMID 29136648, 2017). "Male infertile patients or patients with abnormal sperm parameters are more likely to resort to ART, so the altered epigenetic state of the SNRPN gene (in this case a higher methylation and thus a lower expression) could be transmitted to offspring and lead to imprinted disorders such as PWS." (PMID 38398047, 2024).
lupus (7 papers, 2007 to 2025). "Four proteins, SNRPB/SNRPN, OGN, IFI27, FBLN2, identified only in extracellular vesicles in the blood of CLE patients were also proteins reported to be related to lupus and inflammation." (PMID 41614843, 2025).
male infertility (5 papers, 2019 to 2024). The inability of the male to effect fertilization of an ovum after a specified period of unprotected intercourse. "The first finding supports what has already been reported in the previous meta-analysis on this topic, suggesting the association between increased SNRPN methylation status at sperm level and abnormal sperm parameters and/or male infertility." (PMID 38398047, 2024). "We examined methylation of the ICRs of H19, MEST, KCNQ1OT1 and SNRPN, genes previously reported to be altered in male infertility and/or regions known to have roles in imprinting disorders." (PMID 36611168, 2023). "A recent meta-analysis has confirmed this association between male infertility and aberrant sperm DNA methylation, in particular for imprinted regions H19, MEST, and SNRPN." (PMID 31462300, 2019). "These premises lead us to hypothesize that the methylation status of the SNRPN gene at the sperm level may play a role in male infertility." (PMID 38398047, 2024). "Importantly though, a number of studies have reported an association between male infertility and aberrant sperm DNA methylation for the genomic imprinted regions H19, MEST, and SNRPN." (PMID 31462300, 2019).
acute myeloid leukemia (3 papers, 2016 to 2022). Acute myeloid leukemia (AML) is a group of neoplasms arising from precursor cells committed to the myeloid cell-line differentiation. "SNRPN hyper-methylation was observed in some diseases, 34.9% in myelodysplastic syndrome and 50% in acute myeloid leukemia." (PMID 33224876, 2020).
autism spectrum disorder (3 papers, 2016 to 2024). A spectrum of developmental disorders that includes autism, and Asperger syndrome. "In one of these cases, the patient was identified as a carrier of a duplication in chromosome 15q11.2:q11.2 (SNRPN + +), which is associated with autism spectrum disorder." (PMID 37957533, 2024). "Furthermore, hypermethylation of sperm SNRPN occurring in older men might represent a possible mechanism of age-related impairment of sperm quality and provide insight into the pathogenesis of the risk of autism spectrum disorders in the offspring of fathers with advanced age." (PMID 38398047, 2024).
breast carcinoma (3 papers, 2017 to 2021). "Hypomethylation for the SNRPN gene has also been linked to breast cancer and seminoma." (PMID 34906185, 2021). "This was confirmed using DNA FISH in the breast cancer cell line HCC1954 that has an internal amplification of 15q11.2-12 including SNRPN that does not encompass the nearby centromere." (PMID 28883545, 2017).
Cognitive impairment (3 papers, 2021 to 2022). Abnormal cognition is characterized by deficits in thinking, reasoning, or remembering. "Mice with a targeted deletion of SNORD116 show cognitive deficits, abnormal growth and feeding, while mice with paternal deletions of portions of SNURF or SNRPN seem to have a normal phenotype." (PMID 34200226, 2021).